ELF5 (E74 like ETS transcription factor 5)
Diseases named in the same sentence as ELF5 in open-access papers (continued):
Sharing a sentence is not in itself a finding about the gene and the disease.
cancer (continued). "TCGA data showed an increased diversity of ELF5 isoform expression in cancer compared with the normal breast; therefore, the expression levels and effects of ELF5 isoform expression were examined in vitro to determine if this was of functional consequence." (PMID 26738740, 2016). "The normal human breast expresses relatively high levels of ELF5, with subtype-specific alterations in cancer." (PMID 26738740, 2016). "This understanding of expression and function at the isoform level is a vital first step in realizing the potential of transcription factors such as ELF5 as prognostic markers or therapeutic targets in cancer." (PMID 26738740, 2016). "ELF5 isoform expression was found to be tissue-specific due to alternative promoter use but altered in multiple cancer types." (PMID 26738740, 2016). "In the luminal A, luminal B, and HER2 subtypes, all ELF5 isoforms were decreased in cancer compared with normal." (PMID 26738740, 2016). "This study represents the first comprehensive analysis of ELF5 expression at the isoform level, using RNA-sequencing (RNA-seq) data from The Cancer Genome Atlas (TCGA) for 6757 normal tissue and cancer samples." (PMID 26738740, 2016). "This study has characterized the expression pattern and functions of ELF5 at the isoform level, demonstrating significantly altered expression in cancer." (PMID 26738740, 2016). "RNA-seq data from TCGA were analyzed to quantify and compare ELF5 isoforms in normal and cancer tissues." (PMID 26738740, 2016). "RNA-sequencing data for 6757 samples from The Cancer Genome Atlas were analyzed to characterize ELF5 isoform expression in multiple normal tissues and cancers." (PMID 26738740, 2016). "The kidney, one of the highest ELF5-expressing tissues, showed a dramatic decrease in ELF5 level in cancer." (PMID 26738740, 2016). "EGFP+ cells were compared to WT cells from primary cancers to discover functions altered by ELF5 induction, shown by the inner node color, while the outer node color shows how these functions changed in EGFP+ primary compared to EGFP+ lung metastasis." (PMID 26717410, 2015). "The four genes (HES1, PRKCH, ELF5 and TM4SF1) validated above have all been associated with cancer progression." (PMID 26356672, 2015). "These ranked lists were used as the input for GSEA, to allow comparison of the transcriptional response correlated with increased ELF5 expression in human luminal cancers." (PMID 26717410, 2015). "Third, the Elf5 gene is hypermethylated in cancer cells, so that expansion of the mesenchymal compartment and subsequent SCs is induced and sustained." (PMID 25629735, 2015). "ELF5 expression was lower in cancer compared to patient-matched and micro-dissected normal mammary epithelium, and a series from Sgroi and colleagues found ELF5 was one of the most consistently downregulated genes at all stages of breast carcinogenesis." (PMID 23300383, 2012). "Collectively our ChIP approach has identified numerous mouse target genes of Elf5 and has offered insight into the regulatory pathways controlled by Elf5 during mammary gland morphogenesis and cancer." (PMID 20831799, 2010). "The identification of Ccnd2 as a direct target of Elf5 is a novel finding and has implications for the proliferative decisions of mammary epithelial cells during normal development as well as in cancer." (PMID 20831799, 2010). "In luminal A BC-subtype cell lines MCF-7 and T47D, ELF5 expression inhibits proliferation, whereas ELF5 promotes cell proliferation in basal-like BC cell lines, suggesting that the role of ELF5 could be cancer subtype-dependent." (PMID 38275872, 2024). "However, once cancer has initiated, the connection between age and ELF5 expression or methylation appears to diminish." (PMID 38275872, 2024).
cancer (continued). "However, there is a potential contradiction in that induction of ELF5 to luminal cancer using the MMTV-PyMT mouse model shows that ELF5 increases the size and number of lung metastases." (PMID 38275872, 2024). "Since endocrine-therapy-resistant cells tend to induce ELF5 expression, ER+ cancer cells deriving from ER− luminal epithelial cells progenitors may be predisposed to developing resistance." (PMID 38275872, 2024). "Such plasticity could explain the diversity in ELF5 expression among ER+ cancers, potentially depending on whether the cancer cells originate from ER+/ELF5− or ER−/ELF5+ luminal epithelial cells progenitors." (PMID 38275872, 2024). "ELF5 and its ETS family have been confirmed to regulate angiogenesis in cancers, so we conducted assays to determine whether ELF5 regulates angiogenesis in RCC." (PMID 37980532, 2023). "Hence, the functional role and regulatory mechanism of ELF5 in cancer tumorigenesis and progression are still largely unclear." (PMID 33742100, 2021). "ELF5 levels are low in airway cells but higher in LNCaP (prostate) and T47D (breast) cancer cells." (PMID 31557407, 2019). "More recently, there has been increasing interest in the role of ELF5 in cancer." (PMID 26738740, 2016). "The breast is the most well-studied context for the role of ELF5 in cancer, with microarrays showing increased expression in basal-like subtypes and decreased expression in luminal A/B and Erb-b2 receptor tyrosine kinase 2 (HER2)-overexpressing subtypes, suggesting subtype-specific effects." (PMID 26738740, 2016). "Alterations in ELF5 isoform expression in cancer may drive abnormal cell fate decisions, suggesting that ELF5, like other ETS factors, may be a significant contributor to tumorigenesis." (PMID 26738740, 2016). "Interestingly, ELF5 is localized to human chromosome 11p13-15, a region of the genome, which undergoes loss of heterozygosity (LOH) in many types of cancer, including ductal carcinoma of the breast." (PMID 20831799, 2010). "Therefore, we confirmed that ELF5 exerted the anti-cancer effect in RCC." (PMID 37980532, 2023). "Cancer cells may become insensitive to estrogen when ELF5 increases." (PMID 31895944, 2020). "In this study, we examined the expression patterns of seven core genes (ARRDC5, ELF5, FIBCD1, LINC00494, NLRP7, L1CAM) across multiple cancer types using a combination of unpaired and paired samples, along with data from the TCGA-GTEx datasets." (PMID 39697539, 2024). "Through comprehensive genomic, epigenomic, and transcriptomic dissections, we pinpointed ARRDC5, ELF5, FIBCD1, LINC00494, NLRP7, and L1CAM as possible prognostic indicators across multiple cancer types." (PMID 39697539, 2024). "In the physiological context, Elf5 is demonstrated to be functioned as a suppressor of EMT and cancer invasion." (PMID 25629735, 2015). "Interestingly the mitogenic genes that are repressed by forced ELF5 expression in ER+ T47D cells are generally highly expressed in ER− cancers, showing again that ELF5 has a subtype-dependent role in cell proliferation and may contribute to the proliferative drive in ER− cancers." (PMID 23300383, 2012). "ELF5 is mainly expressed in epithelial cells and function as a suppressor of EMT of cancer cells." (PMID 37980532, 2023). "E74-like transcription factor 5 (ELF5) belongs to the E26 transformation-specific (ETS) family which can modulate genes involved in cell proliferation, differentiation, apoptosis, and metastasis in human cancers." (PMID 37980532, 2023). "ELF5 is located within close proximity of the related ESE member EHF on chromosome 11p13, and analysis of a panel of various cancer cell lines indicates that EHF and ELF5 are amplified or deleted in the same cases, making identification of the driver gene in these cases challenging." (PMID 30200227, 2018). "There was no clear relationship between ELF5 expression and American Joint Committee on Cancer stage." (PMID 26738740, 2016).
cancer (continued). "The mechanisms regulating ELF5 in different tissues and in cancer have not been widely studied; however, in the early embryo and the developing mammary gland, ELF5 regulation of lineage specification is associated with promoter methylation status." (PMID 26738740, 2016). "Notably, ER+ luminal cancer cell lines like T47D and MCF-7 express ELF5 and exhibit proliferation." (PMID 38275872, 2024). "ELF5 has not been direct connected to HCC, but has been associated with a wide range of cancers." (PMID 34766125, 2020). "This study is the first detailed analysis of ELF5 isoform expression and function, extending previous ELF5 Northern blot analysis, immunohistochemistry, and microarray studies to the isoform level using 6757 sequenced normal and cancer samples." (PMID 26738740, 2016).
Bladder (2 papers, 2016 to 2022). "Tumors overproducing PTHrP also displayed increased expression of nuclear pSTAT5 and Elf5, increased expression of markers of secretory differentiation and milk constituents, and histologically resembled secretory carcinomas of the breast." (PMID 35440032, 2022).
infection (1 paper, 2015). The state of being infected such as from the introduction of a foreign agent such as serum, vaccine, antigenic substance or organism. "Accordingly, restoration of Elf5 by infection or demethylating treatment effectively reversed EMT processes." (PMID 25629735, 2015).
ELF5 also shares sentences with these, for which no sentence is quoted: triple-negative breast carcinoma (3 papers); colon carcinoma (2); colorectal cancer (2); Luminal Breast Cancer (2); renal cell carcinoma (2); asthma (1); bladder urothelial cancer (1); chronic myeloid leukemia (1); CNS tumors (1); colon adenocarcinoma (1); congenital heart disease (1); diabetes (1); Ewing sarcoma (1); extraskeletal myxoid chondrosarcoma (1); gastric adenocarcinoma (1); gastric cancer (1); hepatocellular carcinoma (1); invasive ductal carcinoma (1); kidney diseases (1); liposarcoma (1); metastatic disease (1); multicystic mesothelioma (1); myocardial infarction (1); non-small cell lung carcinoma (1); phyllodes tumor (1); Prostate Tumor (1); sarcoma (1); skin cancer (1); testicular cancer (1); uterine endometrioid carcinoma (1).
A further 1 disease shares a sentence with ELF5 in 1 paper.